DPYSL3 (dihydropyrimidinase like 3)
Description:
Necessary for signaling by class 3 semaphorins and subsequent remodeling of the cytoskeleton. Plays a role in axon guidance, neuronal growth cone collapse and cell migration (By similarity).
Synonyms: DRP-3; CRMP-4; ULIP-1; CRMP4; DRP3; ULIP; LCRMP
Tractability: PROTAC: ubiquitination databases record sites on it; its protein half-life has been measured.
Gene: Protein-coding gene on chromosome 5 (147,390,808 to 147,510,089, reverse strand). Ensembl gene ENSG00000113657.
Subcellular location: Cytoplasm; Cell projection, growth cone
Subcellular location (Human Protein Atlas): Cytosol
Pathways (Reactome):
Developmental Biology: CRMPs in Sema3A signaling
Gene Ontology:
Molecular function: filamin binding; protein binding; chondroitin sulfate binding; dihydropyrimidinase activity; identical protein binding; SH3 domain binding; hydrolase activity; hydrolase activity, acting on carbon-nitrogen (but not peptide) bonds; phosphoprotein binding
Biological process: actin crosslink formation; actin filament bundle assembly; cellular response to cytokine stimulus; negative regulation of cell migration; negative regulation of neuron projection development; positive regulation of filopodium assembly; positive regulation of neuron projection development; pyrimidine nucleobase catabolic process; response to axon injury; neuron development
Cellular component: cell body; cytosol; exocytic vesicle; extracellular region; filamentous actin; growth cone; lamellipodium; cytoplasm; synapse
Genetic constraint (gnomAD): Loss-of-function variants: 16 observed, 62.08 expected, observed/expected ratio (o/e) 0.26, 90% interval 0.17 to 0.39. The upper end of that interval is the gene's LOEUF score, 0.39, which puts it in group 1 of 6, group 1 being the genes least tolerant of losing a copy. Missense variants: 693 observed, 892.77 expected, observed/expected ratio (o/e) 0.78, 90% interval 0.73 to 0.83. Synonymous variants: 327 observed, 342.4 expected, observed/expected ratio (o/e) 0.96, 90% interval 0.87 to 1.05.
Homologues: Orthologues: chimpanzee DPYSL3 (100% identical), macaque DPYSL3 (99% identical), pig DPYSL3 (98% identical), guinea pig DPYSL3 (98% identical), rabbit DPYSL3 (98% identical), rat Dpysl3 (97% identical), dog DPYSL3 (97% identical), tropical clawed frog dpysl3 (84% identical), mouse Dpysl3 (81% identical), zebrafish dpysl3 (66% identical). Paralogues in human: DPYSL2 (69% identical), CRMP1 (68% identical), DPYSL4 (58% identical), DPYS (44% identical), DPYSL5 (42% identical).
Diseases named in the same sentence as DPYSL3 in open-access papers:
DPYSL3 is named in the same sentence as 51 diseases in open-access papers, as found by Europe PMC text mining. Sharing a sentence is not in itself a finding about the gene and the disease. The quoted sentences say what the papers report.
prostate carcinoma (19 papers, 2014 to 2022). A carcinoma that arises from epithelial cells of the prostate gland. "We also re-analyzed a published cDNA microarray dataset generated from prostate cancer tissues and identified a clear association of DPYSL3 gene reduction along with disease progression from primary cancer to castration-resistant metastatic cancers." (PMID 27014974, 2016). "There are two transcriptional variants of DPYSL3 gene in human genome, of which the variant 2 is the dominant transcript (DPYSL3v2, CRMP4a) but is also significantly down-regulated in primary prostate cancers." (PMID 27014974, 2016). "Therefore, up-regulating DPYSL3 gene expression in prostate cancer is expected to suppress tumor metastasis, providing a significant benefit for locally advanced high-risk prostate cancer patients." (PMID 27014974, 2016). "In this study, we provided further evidences that DPYSL3 gene expression (variant 2 only) is significantly lower in primary prostate cancers than that in benign tissues and that CRMP4a protein levels are largely reduced in prostate cancers compared to the surrounding benign tissues." (PMID 27014974, 2016). "In prostate cancer, overexpression of DPYSL3 decreased the cellular invasion and inhibited tumor metastasis." (PMID 34363020, 2021). "DPYSL3 is also reported to play a role in cell migration and metastasis suppression in liver and prostate cancer." (PMID 32121246, 2020). "While in prostate cancer, overexpression of DPYSL3 decreased the cellular invasion and inhibited tumor metastasis." (PMID 29514686, 2018). "In attempt to develop a novel anti-metastasis therapy for prostate cancer, we utilized the newly established saRNA technique to up-regulate the expression of tumor metastasis suppressor DPYSL3 gene." (PMID 27014974, 2016). "Analysis of one dataset from publically available OncomineTM database revealed that DPYSL3 expression was largely reduced in metastatic prostate cancer tissues compared to benign prostatic tissues (about 20-fold) and primary prostate cancers (about 15-fold)." (PMID 27014974, 2016). "To understand if DPYSL3 isoforms are differently expressed in prostate cancer tissues, we conducted a real-time PCR analysis of prostate tissues obtained from radical prostatectomy." (PMID 27014974, 2016). "In prostate cancer, the expression of both DPYSL3 mRNA and protein was inversely associated with lymph node metastasis and VEGF expression, and forced DPYSL3 expression in cell lines decreased metastasis in a mouse metastatic model." (PMID 25096402, 2014). "DPYSL3 has been identified as a metastatic suppressor gene in prostate cancer." (PMID 30340426, 2018). "Thus, we hypothesized that saRNAs with optimal properties can be used to increase the expression of silenced tumor suppressor genes such as DPYSL3 in prostate cancers." (PMID 27014974, 2016). "Moreover, treatment of C4-2 and LNCaP prostate cancer cells using an orthotopic xenograft tumor model in athymic mice with the aptamer-saRNA chimera revealed a significant suppression of distal metastasis, as well as enhanced DPYSL3 expression in xenograft tissues." (PMID 30340426, 2018). "The target gene in this study is Dihydro-pyrimidinase-like 3 (DPYSL3, protein name CRMP4), which was identified as a metastatic suppressor in prostate cancers." (PMID 27014974, 2016). "We confirmed our discovery of unknown EMT genes in prostate cancer by testing expression of LSR, S100A14, and DPYSL3 in a PC3 prostate cancer cell line model of EMT." (PMID 28651527, 2017). "We found three groups of genes in the EMT differentially expressed list: a) known EMT genes (e.g. CDH1, ZEB1, TGFB, CDH2, VIM, TIMP1), b) EMT genes previously unknown in prostate cancer (LSR, S100A14, DPYSL3) and c) novel EMT genes (including C1orf116)." (PMID 28651527, 2017).
prostate carcinoma (continued). "Further investigation confirmed DPYSL3 gene/CRMP4 protein as a tumor metastasis suppressor because CRMP4a overexpression led to suppressed tumor cell motility in vitro and metastasis in vivo of prostate cancer cells." (PMID 27014974, 2016). "In addition, we also identified EMT genes that had only been described in a sub-set of malignant disease states, but were previously unknown in prostate cancer (e.g. LSR, S11A14, DPYSL3), implying a common EMT program across multiple cancer types." (PMID 28651527, 2017).
lung carcinoma (11 papers, 2013 to 2022). "Although further exploration is required to clarify the underlying molecular mechanism how TTK regulates DPYSL3 expression and then potentiates malignant behavior, our study offers a valuable insight for the specific management patients with lung cancer." (PMID 32121246, 2020). "In order to further analyze the role of DPYSL3 in progression and invasion of lung cancer, we first observed the motility changes of LLC cells caused by knockdown DPYSL3." (PMID 29514686, 2018). "Furthermore, the occurrence of metastasis was inversely associated with the expression level of DPYSL3 in lung cancer patients." (PMID 29514686, 2018). "Furthermore, we confirmed that the increased TGFβ-induced epithelial-mesenchymal transition (EMT) caused by knockdown DPYSL3 might be responsible for metastasis of lung cancer." (PMID 29514686, 2018). "In addition, DPYSL3 at 5q32 was recently found to correspond to 1 of 3 additional lung cancer susceptibility loci in a genome-wide association study, suggesting the possibility that DPYSL3 may be involved in development of lung cancer." (PMID 24339867, 2013). "MSN is a member of the ezrin–radixin–moesin family of proteins involved in various aspects of cell migration, adhesion, and invasion, and DPYSL3 and heat-shock chaperonin (HSP60) were linked to lung cancer metastasis." (PMID 35512017, 2022). "TTK and DPYSL3 upregulation was positively correlated with a poor clinical outcome in patients with lung cancer." (PMID 32121246, 2020). "In this study, we observed the effect of DPYSL3 on cell motility, migration and invasion of lung cancer cells and analyzed the role of it in xenograft model." (PMID 29514686, 2018). "The correlation between DPYSL3 expression and the survival time of lung cancer patients were analyzed in KMPLOT database." (PMID 29514686, 2018). "Our results suggested that DPYSL3 had influence on motility, migration and invasion of lung cancer cells." (PMID 29514686, 2018). "We also evaluated the effects of DPYSL3 on metastasis using a DPYSL3-positive highly metastatic lung cancer cell line, NCI-H460-LNM35, which we previously generated through in vivo selection." (PMID 24339867, 2013). "Another study reported that DPYSL3 could reduce the ability of motility, migration, and invasion of lung cancer cells." (PMID 34363020, 2021). "DPYSL3 knockdown promoted TGFβ-induced EMT in lung cancer cells." (PMID 34363020, 2021). "Moreover, the DPYSL3 levels in the tumor of lung cancer patients were negatively correlated with the overall survival in two databases (ProgGeneV2, KM plotter and GSE31210)." (PMID 32121246, 2020). "In this study, we confirmed that DPYSL3 regulated the metastasis of lung cancer." (PMID 29514686, 2018). "Next, we analyzed the expression level of DPYSL3 in lung cancer patients." (PMID 29514686, 2018). "In order to analyze the lung cancer metastasis related components, we performed a screening assay and found that the dihydropyrimidinase Like 3 (DPYSL3) might contribute to the occurrence of metastasis in lung cancer." (PMID 29514686, 2018). "Furthermore, the activity of RhoA, which promoted the metastasis of lung cancer, increased with the knockdown of DPYSL3." (PMID 29514686, 2018). "Our previous screening assay indicated that DPYSL3 might be a candidate metastatic lung cancer related molecule." (PMID 29514686, 2018). "Therefore it aroused our interest to ask what was the role of DPYSL3 in the metastasis of lung cancer." (PMID 29514686, 2018). "The expression level of DPYSL3 decreased in lung cancer patients with distant metastasis." (PMID 29514686, 2018). "Together, our findings revealed a novel mechanism underlying the oncogenic potential effect of TTK and clarified its downstream factors NTS and DPYSL3 might represent a novel, promising candidate oncogenes with potential therapeutic vulnerabilities in lung cancer." (PMID 32121246, 2020). "The correlation between DPYSL3 and lung cancer metastasis was still unknown." (PMID 29514686, 2018).
lung carcinoma (continued). "Therefore, in this study, we further analyzed the role of DPYSL3 in lung cancer metastasis." (PMID 29514686, 2018). "The correlation of DPYSL3 and TTK expression was also observed in the sequential tissue section of tumor part of lung tissue obtained from patients with lung cancer." (PMID 32121246, 2020). "In order to elaborate the underlying molecular mechanisms of how DPYSL3 regulated the metastasis of lung cancer, we focused on the EMT changes and confirmed that knockdown DPYSL3 promoted TGFβ-induced EMT in LLC cells." (PMID 29514686, 2018).
pancreatic cancer (11 papers, 2013 to 2023). "In contrast, DPYSL3 is positively associated with metastasis and a poor outcome in breast cancer, renal cell carcinoma, gastric and pancreatic cancer." (PMID 32121246, 2020). "DPYSL3 is associated with malignant gastric and pancreatic tumors." (PMID 28651527, 2017). "Some authors debrided DPYSL3 as a metastasis suppressor, while others reported it facilitates pancreatic cancer cell dissemination via a strong interaction with other cell adhesion factors, including Ezrin, focal adhesion kinase and c-SRC." (PMID 36870971, 2023). "Alternatively, DPYSL3 promoted adhesion and migration in pancreatic cancer cells in vitro as well as metastasis in vivo via activation of other cell adhesion genes." (PMID 25096402, 2014). "Since a dysfunction of cellular adhesion was observed in pancreatic cancer cells treated with siDPYSL3, we further examined the role of DPYSL3 in cell adhesion." (PMID 24339867, 2013). "Our observations revealed that DPYSL3 regulated the adhesion and migration abilities of pancreatic cancer cells in vitro as well as metastasis in vivo." (PMID 24339867, 2013). "Our findings suggest the possible existence of interplay among components of the focal adhesion complex, in which DPYSL3 is crucially involved, and regulates the adhesion and migration of pancreatic cancer cells." (PMID 24339867, 2013). "We further evaluated the effects of DPYSL3 on metastasis using a DPYSL3-positive pancreatic cancer cell line, CFPAC-1." (PMID 24339867, 2013). "We identified a protein, dihydropyrimidinase-like 3, as highly expressed in human pancreatic ductal adenocarcinoma tissues as well as pancreatic cancer cell lines." (PMID 24339867, 2013). "In the present study, we found that the levels of phosphorylation of EZR and c-Src are regulated by DPYSL3 in pancreatic cancer cells." (PMID 24339867, 2013). "In pancreatic cancer, inhibition of DPYSL3 reduced cellular invasion." (PMID 29514686, 2018). "Kawahara and collaborators reported the use of proteomic profiling through iTRAQ for identifying a number of proteins differentially abundant between cancerous and normal pancreatic duct epithelium, with higher abundance of dihydropyrimidinase-like 3 (DPYSL3) in human pancreatic cancer." (PMID 28265552, 2017). "Data from the expression analysis of interacting genes also support the hypothesis that DPYSL3 has an oncogenic function in GC as with pancreatic cancer." (PMID 25096402, 2014). "Since focal adhesion is known to regulate cell migration, we next investigated the role of DPYSL3 in pancreatic cancer cell migration and found acquisition of the enhanced motile phenotype in DPYSL3-introduced PANC-1 cells in vitro, as shown by a motility assay as well as a matrigel invasion assay." (PMID 24339867, 2013). "In the present study, we searched for proteins differentially expressed between cancerous and normal pancreatic duct epithelium through proteomic profiling with iTRAQ, which resulted in the identification of high expression of dihydropyrimidinase-like 3 (DPYSL3) in human pancreatic cancer." (PMID 24339867, 2013). "Therefore, it would be interesting to elucidate the detailed signaling pathway(s) leading to phosphorylation of DPYSL3 as well as the functional significance of that phosphorylation in the adhesion and migration processes of pancreatic cancer cells." (PMID 24339867, 2013). "Given that it has important roles in regulating the motile phenotype of pancreatic cancer cells, DPYSL3 may be a candidate for antimetastasis therapeutic strategies, which may ultimately lead to a reduction in the large number of deaths caused by this devastating disease." (PMID 28265552, 2017). "Given that it has important roles in regulation of motile phenotype of pancreatic cancer cells, DPYSL3 may be an excellent candidate for anti-metastasis therapeutic strategies, which may ultimately lead to a reduction in the large number of deaths caused by this devastating disease." (PMID 24339867, 2013).
pancreatic cancer (continued). "Next, we examined whether DPYSL3 knockdown affects the viability of pancreatic cancer cells." (PMID 24339867, 2013).
gastric cancer (8 papers, 2014 to 2023). A primary or metastatic malignant neoplasm involving the stomach. "A previous study showed that increased DPYSL3 expression promotes tumour aggressiveness in pancreatic ductal adenocarcinoma, gastric cancer, and colon cancer." (PMID 37380971, 2023). "According to studies, the DPYS subtype DPYSL3 was a potential biomarker for stomach cancer’s malignant nature." (PMID 37999212, 2023). "In another recent study analyzing mRNA and protein expression in surgically resected gastric tissues and gastric carcinoma cells, CRMP-4 (Dpysl3) was identified as a potential facilitator of malignant behavior and as an independent prognostic factor in gastric carcinoma." (PMID 26934554, 2016). "A previous study in gastric cancer showed that modulating the expression of the short DPYSL3 isoform induces G1-phase arrest but not apoptosis." (PMID 37380971, 2023).
breast carcinoma (7 papers, 2020 to 2024). "In claudin-low breast cancer cells, DPYSL3 mRNA and the epithelial-mesenchymal transition (EMT) markers SNAIL and TWIST can regulate each other reciprocally." (PMID 37380971, 2023). "For example, in dihydropyrimidinase-like 3 (DPYSL3)-positive breast cancer CLOW cells, cell proliferation decreases and the expression of marker genes in epithelial-mesenchymal transformation increases in the DPYSL3 knockdown group." (PMID 35664322, 2022). "In breast cancer, DPYSL3 knockdown determined a reduced proliferation, but a still enhanced motility and increased expression of epithelial-to-mesenchymal transition markers, suggesting that DPYSL3 is a multifunctional signaling modulator." (PMID 36870971, 2023). "Dihydropyrimidinase-like-3 (DPYSL3) has been reported to modulate mitosis, migration, and epithelial–mesenchymal transition (EMT) in breast cancer." (PMID 38240752, 2024).
neuroblastoma (7 papers, 2010 to 2023). Neuroblastoma (NB) is the most common solid, extracranial childhood tumor. "DPYSL3 was found abundant in the cytosol of B35 neuroblastoma cells and to co-localizes with F-actin in regular rib-like structures within lamellipodia of these cells, with which physically interacts." (PMID 36870971, 2023). "In neuroblastoma cells, it has been shown that DPYSL3 regulates the actin cytoskeleton, whose dynamic reorganization is known to be fundamental for cell migration." (PMID 36870971, 2023). "Previous studies indicated that DPYSL3 inhibits cell migration by regulating the actin cytoskeleton in neuroblastoma cells." (PMID 32121246, 2020). "The critical functional equilibrium between DPYSL3 and F-actin is demonstrated by the fact that DPYSL3 overexpression inhibited the migration of B35 neuroblastoma cells, while its knockdown enhanced cell migration and disturbed rib-like actin-structures in lamellipodia." (PMID 36870971, 2023). "The prognostic role of AHCY, DPYSL3, and NME1 The evaluation of the impact of AHCY, DPYSL3 and NME1 on the prognosis of patients affected by Neuroblastoma showed the importance of these genes in terms of association with the death rate and prediction of the survival probabilities across time." (PMID 36870971, 2023). "Our results pointed out the relevant impact of the genes AHCY, DPYSL3 and NME1 on neuroblastoma prognosis as future targets for future neuroblastoma genetics studies and the development of novel therapies." (PMID 36870971, 2023). "In the following text, we report a description of the relevant role of AHCY, DPYSL3, and NME1 in neuroblastoma development highlighted by the studies considered by the state-of-the-art literature, as described in subsection Validation on the literature." (PMID 36870971, 2023).